BMI1 (BMI1 proto-oncogene, polycomb ring finger)
Diseases named in the same sentence as BMI1 in open-access papers (continued):
Sharing a sentence is not in itself a finding about the gene and the disease.
cancer (continued). "Transcriptome analyses revealed upregulation of several transcription factors involved in cancer stemness/EMT, including Twist 1/2, Slug, Snail1, and Bmi1, by MB21D2 overexpression or its Q311E mutant." (PMID 32979859, 2020). "In this study, we observed that the mRNA and the protein levels of Bmi1 were strictly inconsistent in NPC cell lines and cancer tissues." (PMID 33014838, 2020). "ALDH+CD44+ cancer cells transfected with siPDK4 exhibited lower expression of OCT4, KLF4, and BMI1 genes at both mRNA and protein levels." (PMID 32390009, 2020). "(BMI1, also called PCGF4) is involved in embryonic development, cell cycle regulation, DNA damage response, senescence, stemness and cancer." (PMID 32708145, 2020). "Other groups have also shown a physical interaction between BMI-1 and MUC1-C in other cancers, suggesting a putative post-transcriptional regulation of cPRC1 activity by MUC1-C." (PMID 33126754, 2020). "B lymphoma Mo-MLV insertion region 1 homolog (BMI1) advances the EMT and stemness of cancer cells via promoting NF-κB-mediated NANOG expression." (PMID 33066509, 2020). "Considering the intimate connection between EMT and cancer stemness, we further examined the expression of six key biomarkers of cancer stemness (NANOG, SOX2, OCT4, CD44, ABCG2, BMI1)." (PMID 32863941, 2020). "Thus, there is a possibility that new cancer treatment may potentially target Bmi-1 elevation." (PMID 32059385, 2020). "Several transcription factors, including BMI1, LGR5, NANOG, OCT4, and SOX2, are upregulated in various cancer types and promote stemness maintenance, local tumor invasion, and distant metastasis." (PMID 30866999, 2019). "This review focuses on the latest advances in our understanding regarding the crosstalk of Wnt5a-ROR1 and Hippo-YAP/TAZ or BMI-1 in tumorigenesis and drug resistance and discusses novel strategies for the therapeutic targeting of ROR1 in cancer treatment." (PMID 31382410, 2019). "Recent studies have demonstrated the indispensable role of Bmi1 in sustaining CSC renewal and CSC-mediated tumorigenesis in various cancer types including breast cancer." (PMID 30918246, 2019). "Bmi-1 plays a role in some biological functions including senescence, self-renewal, DNA damage response (DDR), and cancer." (PMID 31346357, 2019). "Altogether, our study illustrates that USP2 overexpression in TNBC promotes Twist/Bmi1 expression, CSC expansion, cancer cell migration and tumor development." (PMID 30918246, 2019). "Taken together, our data revealed inhibition of BMI1 using PTC-209 to induce increased DNA damage and to induce apoptosis in cancer cells." (PMID 31548560, 2019). "MiR-203 is a cancer suppressor that interacts with different genes involved in hepatocarcinogenesis, such as EZH2 and BMI1, SURVIVIN, RASAL2, ADAM9, and MMP2." (PMID 31073374, 2019). "This review focuses on the crosstalk between Wnt5a-ROR1 and YAP/TAZ or the BMI-1 signaling network, together with the current advancements in targeted strategies for ROR1-positive cancers." (PMID 31382410, 2019). "Bmi-1 (a member of PRC1) serves as the gene silencer that induces cellular senescence and cell death, and it can contribute to cancer when improperly expressed." (PMID 30072631, 2018). "miR-15a inhibits several important genes (BCL2, BMI1, YAP1 and DCLK1), decreasing cancer progression and resistance." (PMID 29416778, 2018). "The commonly reported specific surface markers, such as CD44, CD133, OCT-4, Bmi-1, ALDH1, ABCG2 and KLF4, with high expressions, are usually used to isolate cancer stem cells from cell lines." (PMID 29559853, 2018). "Here, we show that BMI-1 is highly expressed in tumor tissue samples of DIPG patients and in patient-derived cancer stem-like cells." (PMID 28968963, 2017). "We also detected other cancer stem cell-related genes in the putative A549 stem cells, and found that CXCR4, NESTIN, BMI1 gene levels had increased." (PMID 28881812, 2017).
cancer (continued). "Quantitative PCR analyses were performed to measure the transcriptional regulation of cancer stemness markers, such as ALDH-1, CD133, CD44, Lgr-5, Msi-1, EphR1, and Bmi-1, by BP compounds." (PMID 28862656, 2017). "Our results showed that the protein expression of ALDH1 was positively stained in the cytoplasm, whereas BMI1 was in the cytoplasm and nucleus in SCCHN; CD44 was mainly expressed in the membrane of cancer cells but also in the basal layer of normal mucosa." (PMID 28865486, 2017). "Recent pioneering studies have identified PTC-209 as a potent and specific chemical inhibitor of Bmi1 and revealed promising therapeutic efficiency of PTC-209 against cancer." (PMID 29200967, 2017). "Additional cancer stem cell populations have been characterized in human epidermal SCC, including keratin 19, aldehyde dehydrogenase 1, Oct4, and Bmi1." (PMID 29113290, 2017). "Several approaches have been examined in an effort to develop cancer therapeutics targeting BMI112–15, particularly since BMI1 has a significant role in DNA damage response pathway." (PMID 28655885, 2017). "Recent work has further shown that MUC1-C forms a complex with BMI1 in cancer cells, invoking the possibility that MUC1-C also affects BMI1 expression by post-translational mechanisms." (PMID 29050200, 2017). "To determine the functional significance of the BMI1/let‐7i/ERK3 pathway in cancer cells, we decided to study the effects of their interplay on cancer cell migration, a cellular function shared by all of them." (PMID 28079973, 2017). "For instance, studies in carcinoma cells have shown that MUC1-C induces miR-200c by an NF-κB p65-mediated signaling and that miR-200c inhibits BMI1 translation." (PMID 29050200, 2017). "BMI1(the parental gene of BMI1P1), a stem cell factor, was observed to be highly expressed in various types of human cancers, including AML." (PMID 27329719, 2016). "BMI1 is a core component of the polycomb repressive complex 1 (PRC1) and emerging data support a role of BMI1 in cancer." (PMID 27827373, 2016). "Because BMI1 and BCL2 have been reported as target genes of miR-15b in cancer, their mRNA levels in OvCa were also examined." (PMID 27195958, 2016). "BMI-1 knockout was shown to upregulate DKK1 and to target cancer cells via subsequent downregulation of MYC and CCND1." (PMID 26935956, 2016). "For instance, miR-429 mediated suppression of EMT has also been correlated with miR-429 directly targets Onecut2, BMI-1 and E2F3, MiR-429 enhances cancer cell apoptosis under chemotherapy by targeting Bcl-2 and AP-2α." (PMID 27058893, 2016). "In cancer cells, we found that metformin activated AMPK, concurrently with upregulation of LIFAF and downregulation of Bmi-1." (PMID 26717043, 2016). "Altogether, our data for the first time suggest a regulatory axis in cancer cells: AMPK upregulates LITAF, which in turn increases miRNAs, leading to attenuation of Bmi-1 expression." (PMID 26717043, 2016). "In conclusion, in the present study, miR-218 was found to be significantly decreased expression in ESCC, and miR-218 targets BMI1 and downregulates its expression in ESCC cells, which is important in regulating cancer cell growth and metastasis." (PMID 25999024, 2015). "Collectively, these data indicate silibinin inhibited HNC tumorigenicity through the activation miR-494-targeting Bmi1 and ADAM10 expression, which resulted in the inhibition of cancer stemness." (PMID 26090866, 2015). "The aberrant expression of BMI1 is involved in cell proliferation, epithelial-mesenchymal transition (EMT), tumor invasion and metastasis in many types of cancer." (PMID 25999024, 2015). "miR-494-targeting Bmi1 and ADAM10 expression would greatly contribute to a deeper understanding of cancer stemness acquisition in HNC, and promote the development of promising therapeutics for HNC-TICs eradication." (PMID 26090866, 2015). "Studies indicated that Bmi-1 promoted the invasion and tumorigenesis and induced EMT in several cancer cells." (PMID 26452029, 2015).
cancer (continued). "However, because p16Ink4a-KO mice die of cancer long before they reach the age at which most normal mice experience a decrease in SMG function, we asked whether p16Ink4a deficiency can rescue the premature decrease in SMG function in Bmi-1-KO mice." (PMID 25832744, 2015). "It has also been reported that Bmi-1 represses the tumor suppressor PTEN and induces EMT in some cancers." (PMID 26452029, 2015). "We also document that like basal-like carcinoma cells, T-MS also express the CK-5/14, EGF-R, CD133, Bmi-1, and IL-6 genes." (PMID 25881039, 2015). "Bmi-1 inhibition protects prostate cells from FGF10-driven hyperplasia and slows the growth of aggressive cancers with PTEN deletion." (PMID 25277175, 2014). "We examined the transcriptional relationship in the BMI-1, p14ARF, c-Myc and cyclin D2 expression by quantitative real-time PCR in the ACC-83 cancer cells." (PMID 24466336, 2014). "BMI1 and EZH2 levels are elevated in several types of cancer and there is increasing evidence that they promote tumor progression by supporting cellular self-renewal and proliferation, while blocking differentiation." (PMID 25249625, 2014). "Several studies have revealed that Bmi1 mainly promotes tumor development by repressing INK4a/ARF locus, which can induce cell senescence and inhibit the proliferation of cancer cells." (PMID 25372945, 2014). "Overall, the results indicate that cell populations that are positive for the putative cancer stem cell markers ABCG2 and Bmi-1 can occur with increased density in malignant or oral potentially malignant lesions, and cell lines derived from them." (PMID 24415717, 2014). "Examination of the expression of 3 cancer stem cell markers, ALDH-1, Bmi-1, and Nanog, in patients with ESCC indicated correlations with TRG but not OS." (PMID 25148045, 2014). "In this study, we found that the CD133+ and BMI-1+ cells are upregulated in OSCC tissues, and act like cancer stem cells." (PMID 24572994, 2014). "To study the effect of Bmi1 knockdown on drug response of NBLE-LP and MDAMB231 cells we treated vector control and shBmi1 cells with anti-cancer drug doxorubicin for 48 hrs." (PMID 25348805, 2014). "BMI1 is a member of the PRC1 complex; it controls many diverse biological cancer processes including differentiation, senescence, proliferation, migration, and tumorigenesis." (PMID 23820733, 2013). "Expression of PcG proteins including BMI1 and EZH2 are often up-regulated in various cancers, particularly in their cancer stem cell fractions." (PMID 22606246, 2012). "Thus, in ESCC patients subjected to CRT, the role of BMI1-mediated inhibition of p16INK4A protein is not clear, and the clinical effect of Hh signalling pathway activation might be more evident than that of the presence of BMI1, whilst BMI1and Gli-1 both play important roles in cancer progression." (PMID 23046527, 2012). "The preferential expression of cancer stem cells related marker (CXCR4), regulatory genes (BMI1, GLI1, and GLI2) and microRNAs (miR-214, miR-21, miR-221, miR-222 and miR-155) in holoclones were also highlighted." (PMID 21826251, 2011). "Moreover, we demonstrated that loss of BMI-1 in EC cells reduces expression of stemness gene SOX-2, KLF4 and drug-resistance gene MRP-1, suggesting that BMI-1 expression maybe required for the proliferation of cancer cells, as well as for regulation of stemness properties of EC cells." (PMID 21851624, 2011). "By exacerbating ROS production inresponse to cisplatin, Bmi-1 silencing activates the DNA damage responsepathway, caspases and cleaves PARP resulting in the induction apoptosis inovarian cancer cells." (PMID 21445297, 2011). "Real-time RT-PCR revealed a higher expression of CENP-F mRNA in all the cancer cell lines than that in NPEC2 and NPEC2 Bmi-1 cells." (PMID 20828406, 2010). "Expression of the key ‘stemness’ genes of embryonic (ES) and induced-pluripotent stem (iPS) cells OCT4 and BMI1 have been found in CSC from different cancers." (PMID 21124918, 2010).
cancer (continued). "Another important target of BMI1 and Mel-18 appears to be AKT, which is known to regulate tumorigenesis and cancer metastasis in several cancers." (PMID 20170541, 2010). "Both the nuclear markers, BMI1 and OCT4, were expressed in the majority of cancer cells in all cell lines studied." (PMID 21124918, 2010). "Bmi1 is a key component of PRC1 regulating chromatin remodeling and gene expression pathways essential for self-renewal of stem cells and cancer stem cells." (PMID 19956605, 2009). "Results demonstrated existence of distinct subsets of cancer cells, which express CTIP2 and underscores the use of CTIP2 and BMI1 co-labeling to distinguish tumor initiating cells or cancer stem cells (CSCs) from surrounding cancer cells." (PMID 19399189, 2009). "The present study underscores the possible use of CTIP2 and BMI1 co-labeling to identify cancer stem cells (CSC) in HNSCC and suggests a transcriptional regulation of Bmi1 gene by CTIP2." (PMID 19399189, 2009). "While PTEN co-localized with BMI1 in 2.4% of normal prostate epithelial cells, co-localization was observed in 37.6% and 18.5% of cells in PIN and carcinoma, respectively." (PMID 19903340, 2009). "While only 2.4% of epithelial cells from normal prostate glands show low levels of co-localization between PTEN and BMI1, 37.6% and 18.5% of PIN and carcinoma cells display extensive co-localization between PTEN and BMI1." (PMID 19903340, 2009). "Further studies identified T-cell responses to both BMI-1 and another PcG protein, EZH2, in cancer patients and at relatively lower levels in some normal donors." (PMID 17024127, 2006). "We have demonstrated that the PcG proteins BMI-1 and EZH2 represent promising target antigens for cancer immunotherapy." (PMID 17024127, 2006). "Furthermore, we also observed the downregulation of the mRNA expression of several key cancer stemness markers following CLF treatment, including CD44, CD24, BMI1, and HES1." (PMID 41303378, 2025). "Furthermore, the expression of cancer stem cell-related markers—ABCG2, Bmi-1, and Nanog—was validated, confirming that SRGN enhances the self-renewal and stemness of malignant HCC cells." (PMID 40384866, 2025). "Although BMI1 lacks intrinsic enzymatic activity, it is indispensable for PRC1’s function, reinforcing its role in gene silencing and establishing its oncogenic potential in a variety of cancers." (PMID 40508013, 2025). "Given that the GSC state is not a stable clonal subpopulation but rather a plastic state induced by the tumor microenvironment, we scored cells based on classic GSC markers (PROM1, SOX2, NES, OLIG2, BMI1, NANOG, POU5F1) and defined the top 2% of cancer cells with the highest stemness scores as GSCs." (PMID 41041071, 2025). "Regardless of advancements in understanding Bmi‐1's contributions to cancer, there remains a significant gap in the literature regarding its role in promoting stemness and how it contributes to therapy resistance." (PMID 39791545, 2025). "Moreover, expression of stemness markers such as BMI1 and CD44 was reduced in metformin-treated cells, suggesting that metformin can also target cancer stem cells." (PMID 39796103, 2024). "The Ink4a–Arf1-independent cancer-promoting mechanism of Bmi-1 has not been fully elucidated and is beyond the scope of this study." (PMID 38141761, 2024). "Thus, we also examined expression levels of HNSCC specific cancer stem cell (CSC) markers, CD44 and ALDH, as well as other markers for HNSCC stemness, SOX2, NANOG, and BMI1." (PMID 38435825, 2024). "Bmi-1 overexpression leads to EMT and enhances cancer stemness in the NSCLC cell line, A549344." (PMID 38164743, 2023). "Thus, it can be concluded that chemoresistant cells are characterized by the accumulation of cancer stem cells and the increased expression of stemness (CD44, CD133, CD10, ALDH) and pluripotency (NANOG, BMI1, OCT4, SOX2) markers." (PMID 37453969, 2023).
cancer (continued). "Third, in vitro functional assays demonstrated that knockdown of BMI1 could significantly attenuate the cancer‐promoting effect of SNHG3 overexpression, suggesting that the SNHG3/c‐MYC/BMI1 axis may play an important regulatory role in BLCa." (PMID 36208024, 2023). "Similarly, another study suggests that suppression of BMI1 promotes autophagic cell death by inducing DDR and ATM in cancer cells." (PMID 37767112, 2023). "YY1 is overexpressed in NSCLC and co-expressed in the NSCLC gene network, probably related with the activation of cell proliferation and invasion, forming a regulatory loop with cancer stem cell transcription factors (SOX2, OCT4, and BMI1) in the NF-kB/PI3K /AKT axis." (PMID 36661515, 2023). "To determine the role of CTSB in BMI1 mediated cancer cell properties, we genetically modified CTSB expression in WBBMI1/PLCBMI and BMI1 depleted MHCC97H cells, indicating that neither CTSB depletion/overexpression affected the proliferation and colony formation in these cells." (PMID 37923799, 2023). "In addition, cancer stemness was enhanced by expression of OCT4 and Bmi-1 alongside tumor sphere formation within ALDHhigh+ and CD133-expressed cancer cells." (PMID 38170015, 2023). "Moreover, BMI1 can induce EMT and metastasis of cancer cells through cooperating with Twist1, a crucial EMT regulator." (PMID 35455671, 2022). "In this study, we found that knockdown of BMI1 blocked LAC cell migration, invasion, chemo‐resistance and tumour initiation in vitro and in vivo, confirming the previous recognition of BMI1 as a stemness regulator in cancer." (PMID 35794816, 2022). "However, silencing of this locus is unlikely to be the only mechanism by which it exerts its oncogenic effects, and BMI-1 has been found to promote stem cell expansion and tumorigenesis in an Ink4a/ARF independent manner in some cancers." (PMID 36076977, 2022). "Consequently, there is an interdependent relationship between the expression of BMI1 and TWIST1 in cancer initiation, differentiation, self-renewal, stemness, EMT, and CSC-mediated metastasis." (PMID 36553636, 2022). "We observed a redistribution of BMI1 proteins from CAP to PcG bodies in replicative breast CSCs but not in mature cancer cells." (PMID 35110528, 2022). "In addition to NANOG, Twist1 and Bmi1 are important factors in the promotion of EMT and are positively correlated with poor prognosis in various cancers." (PMID 36114703, 2022). "Since the proliferative and tumor stemness phenotypes were significantly affected by FAM64A inhibition, we next detected markers reflecting proliferation and cancer stemness, and found that the levels of PCNA, CD44, SOX2, and BMI-1 were all markedly decreased upon reduction of FAM64A." (PMID 35538067, 2022). "Cancer stem cell properties play critical roles in tumorigenesis, progression, and therapy, and SRg3 inhibits self-renewal activity in breast stem-like cancer cells by blocking Akt-induced HIF-1α activation and inhibiting HIF-1α-regulated expression of Bmi-1 and Sox-2." (PMID 36278171, 2022). "We previously demonstrated that B lymphoma Mo-MLV insertion region 1 (BMI1) was increased in pemetrexed resistant NSCLC cells and the inhibition of BMI1 by a small molecule inhibitor suppressed the cancer stem cell activity and increased the pemetrexed sensitivity of the pemetrexed resistant cells." (PMID 36499676, 2022). "In contrast, the high expression of BMI1 increases the self-renewal capacity of cancer cells and may promote EMT and in cancer stem cells (CSCs), BMI1 is also highly expressed." (PMID 36499676, 2022).